MT3 (metallothionein 3)
Diseases named in the same sentence as MT3 in open-access papers (continued):
Sharing a sentence is not in itself a finding about the gene and the disease.
injury (1 paper, 2010). Damage inflicted on the body as the direct or indirect result of an external force, with or without disruption of structural continuity. "By reducing toxic zinc accumulation, LMP, and cell death, downregulation of MT3 function may be beneficial in acute brain injury." (PMID 20974010, 2010).
leukemia (1 paper, 2014). A malignant (clonal) hematologic disorder, involving hematopoietic stem cells and characterized by the presence of primitive or atypical myeloid or lymphoid cells in the bone marrow and the blood. "Transfection of the PLVX-MT3 lentivirus into HL-60 and MV4-11 leukemia cells was found to significantly upregulate expression of MT3 and significantly inhibit cell proliferation." (PMID 24962166, 2014). "Our results showed that the MT3 promoter was hypermethylated in 7/11 leukemia cell lines, with the highest methylation levels observed in HL-60, MV4-11 SHI-1, U937 and K562 cells; whereas it was unmethylated in 4/11 cell lines, 697, SHI-1, THP-1 and Jurkat." (PMID 24962166, 2014). "The apoptotic effect of MT3 in leukemia cells was confirmed by Western blot analysis which showed that MT3 overexpression led to enhanced expression of cleaved PARP, a marker of apoptosis." (PMID 24962166, 2014). "To determine whether MT3 induced apoptosis in leukemia cells, we performed an Annexin V assay in HL-60 and MV4-11 leukemia cells following transfection." (PMID 24962166, 2014). "The MT3 promoter was hypermethylated in leukemia cell lines." (PMID 24962166, 2014). "To confirm methylation of the MT3 promoter, we treated the leukemia cell lines with 5-Aza." (PMID 24962166, 2014). "However, there were no reports on the role of MT3 in leukemia cells." (PMID 24962166, 2014).
male infertility (1 paper, 2023). The inability of the male to effect fertilization of an ovum after a specified period of unprotected intercourse. "Sanger sequencing analysis using genomic DNA and cDNA confirmed that MT3 was homozygous in affected individuals and heterozygous in their father, thus cosegregating with male infertility in the family." (PMID 37485353, 2023).
Menkes kinky-hair syndrome (1 paper, 2013). "Differently expressed isoform analysis showed that the MT3 isoform was up-regulated in Tan lamb skin, suggesting that MT3 is related to the conformation of curly fleece in Chinese Tan lamb skin, since the metallothionein 1 was reported to regulate the Menkes kinky-hair syndrome in mouse." (PMID 23990983, 2013).
myeloid leukemia (1 paper, 2014). A clonal proliferation of myeloid cells and their precursors in the bone marrow, peripheral blood, and spleen. "Our results showed that the MT3 promoter was hypermethylated in seven out of eleven human myeloid leukemia cell lines." (PMID 24962166, 2014). "In summary the hypermethylation status of the MT3 promoter in samples from patients with pediatric AML was consistent with results in human myeloid leukemia cell lines." (PMID 24962166, 2014).
nodular melanoma (1 paper, 2011). "However, increased levels of MT3-MMP are associated with the most aggressive nodular melanoma." (PMID 22164270, 2011). "While the nodular vs. superficially spreading origin of the biopsied tissues of the metastatic lesions had not been defined, MT3-MMP expression was not restricted to nodular melanoma-derived cell lines." (PMID 22164270, 2011).
oesophageal cancer (1 paper, 2005). "We measured MT3 gene expression by RT-PCR, and DNA methylation in the MT3 promoter by combined bisulphite restriction analysis, in four oesophageal cancer cell lines and the resected oesophagus from 64 patients with oesophageal squamous cell carcinoma (SCC)." (PMID 16351731, 2005).
oropharyngeal cancer (1 paper, 2025). Carcinoma, predominantly squamous cell, arising from the epithelial cells of the oropharynx. "Regarding oropharyngeal cancer, NTS, LCE2B, DDC, PCDHGC5, and MT3 demonstrated increased expression levels." (PMID 40255484, 2025).
ovarian endometriosis (1 paper, 2022). A non-neoplastic disorder characterized by the growth of endometrial tissue in the ovaries. "Positive staining for MT3-MMP was further identified in almost all ectopic endometrial epithelial cells: peritoneal, deep infiltrating, and ovarian endometriosis." (PMID 35453827, 2022).
Sepsis (1 paper, 2021). Sepsis is defined as life-threatening organ dysfunction caused by a dysregulated host response to infection. "WT and Mt3-/- mice were challenged with ultrapure LPS (20 mg/kg) and assayed for weight loss, murine sepsis scores (MSS) and survival." (PMID 34867993, 2021). "MT3 deficiency resulted in greater weight loss and increased sepsis scores, but both genotypes similarly succumbed to septic shock." (PMID 34867993, 2021). "Although Mt3-/- mice exerted higher sepsis scores and weight loss, they succumbed to septic shock similar to WT controls, suggesting that a threshold level of caspase-11 activation may be sufficient to promote sepsis-associated mortality." (PMID 34867993, 2021).
tongue cancer (1 paper, 2025). A malignant neoplasm affecting the tongue. "The findings revealed that, in comparison to their levels in normal tissues, the genes GAL, GHRH, LCE2B, PCDHGC5, and MT3 were notably upregulated in tongue cancer, while NTS was downregulated." (PMID 40255484, 2025).
type 2 diabetes (1 paper, 2023). "Mt1 and Mt3 are also involved in protection against oxidative stress and their downregulation in db/db mouse astrocytes may contribute to oxidative damage and enhanced inflammation in the type 2 diabetes cortex." (PMID 37351595, 2023).
tumor (37 papers, 2005 to 2025). "To investigate if MT3 promoter methylation is associated with tumor biology, we performed statistical analysis between DNA methylation and clinicopathological parameters." (PMID 21818286, 2011). "Also, 3 patients with unmethylated DNA had low levels of MT3 expression, perhaps reflecting mutation or other change in the tumour." (PMID 16351731, 2005). "Three of the top upregulated and most highly expressed DEGs in the majority of Ascl1-OE tumor cells are Tmsb4x, Sparcl1, and Mt3." (PMID 39609428, 2024). "MT3 regulates drug resistance in tumor cells by regulating the expression of YAP1, a protein that has been linked to tumor proliferation, invasion, and migration." (PMID 38041044, 2023). "MT3 was a small cysteine-rich protein that played an important role in tumor growth and immune escape." (PMID 36131791, 2022). "Many studies report that MT3 gene knock out is effective in preventing recurrence of tumor due to side effects of these therapies." (PMID 32843100, 2020). "Animal studies found that MT3 was overexpressed in tumor heterotransplants derived from arsenic-transformed human urothelial cells." (PMID 30813460, 2019). "Lastly, MT3 a metallothionein III, has been identified as a tumor suppressor in various cancers as well as in pediatric AML." (PMID 29928480, 2018). "Further in vitro experiments using human ESCC cancer cell line revealed that overexpression of MT3‐MMP inhibited tumor cell growth, whereas down‐regulation of MT3‐MMP by shRNA significantly promotes ESCC cell proliferation." (PMID 27292876, 2016). "Here, we report that MT3‐MMP was down‐regulated in ESCC tumor tissues, which correlates to high metastasis rate and poor survival; therefore, representing a favorable factor for prognosis of patients with ESCC." (PMID 27292876, 2016). "Downregulated factors such as MGMT, p16Ink4A, p27Kip1, Bcl-2, Bax, Bcl-x, and MT3 are involved in the cell cycle, apoptosis, tumor suppression, metabolism, and enhanced TMZ sensitivity." (PMID 27893664, 2016). "More importantly, MT3‐MMP down‐regulation in tumor tissues significantly correlated with higher rate of metastasis and poor survival of patients with ESCC." (PMID 27292876, 2016). "A better understanding of the tumor‐suppressive role of MT3‐MMP would significantly improve our knowledge in tumor progression of ESCC and prognosis of patients with this disease." (PMID 27292876, 2016). "Due to the lack of studies analyzing MT3 expression in human cancer tissues, further research on human tumors seems to be justified, with the aim of elucidating the significance of varying MT3 cellular localizations on tumor progression." (PMID 25933064, 2015). "The results of recent research concerning the role of MT3 in neoplastic diseases remain ambiguous and are frequently inconsistent." (PMID 25015776, 2015). "In the TNBC tumor sections, MT3 immunoreactivity was observed in the nuclei as well as in the cytoplasm of the cancer cells." (PMID 25933064, 2015). "Metallothionein III (MT3) is a tumor suppresser reported to show promoter hypermethylated in various cancers." (PMID 24962166, 2014). "Free CS-4 chains or CS-4 chains on CSPG4 bound to proMMP-2 and MT3-MMP forming a complex that facilitated the activation of proMMP2 by MT3-MMP-expressing tumor cells to enhance invasion and metastasis." (PMID 24205138, 2013). "In spite of many efforts, the role of MT-3 in neoplastic disease remains ambiguous and the results of the studies were frequently inconsistent." (PMID 23273222, 2012). "This is of particular importance in view that MT1-MMP is among the triad of MMPs (MT1- MT2- and MT3- MMPs), essential for invasive behavior of tumor cells." (PMID 22701711, 2012). "In contrast, all specimens of urothelial cancer were immunoreactive for the MT-3 protein, and the intensity of staining correlated to tumor grade." (PMID 21303554, 2011). "This study showed that only 2 of 63 (3.17%) benign bladder specimens had even weak immunostaining for the MT-3 protein." (PMID 21303554, 2011).
tumor (continued). "Immunohistochemistry on an independent series of 24 tumor pairs at diagnosis and at relapse confirmed the decrease of MT3 expression at recurrence in 17/24 tumor pairs (p = 0.002)." (PMID 20885975, 2010). "qPCR analysis were performed for the genes KIF11, ASPM and MT3 in the tumours previously analyzed by gene-expression microarray." (PMID 20885975, 2010). "MT3 expression in methylated tumours was significantly less than that of the matched margin (p = 0.0005)." (PMID 16351731, 2005). "The frequency of MT3 methylation was measured in resected primary tumour and, when available, the proximal resection margin from 64 patients with oesophageal SCC." (PMID 16351731, 2005). "In resected oesophageal SCC tissue MT3 expression was frequently down-regulated, most commonly in those tumours in which the promoter region was methylated." (PMID 16351731, 2005). "MCSP’s functional role involves intracellular signaling pathways related to cell migration, survival, and angiogenesis, as well as interactions with membrane-type 3 matrix metalloproteinase (MT3-MMP) resulting in increased proteolysis of the ECM followed by tumor cell invasion." (PMID 40106404, 2025). "Subsequently, some studies reported that MT3 could regulate the proliferation of tumor cells, but showed different effects in different tumor cells 19-21." (PMID 38904023, 2024). "However, the spatial expression gradient we observed in GFAP and MT3 expression, with upregulation at the tumor-stroma interface in leptomeningeal metastases, suggests that neural damage occurs directly at the tumor/stroma interface." (PMID 38866016, 2024). "The genes with a significant correlation between the level of expression and the spatial proximity between tumor and stromal spots that are enriched in leptomeningeal tissues (patterns observed in multiple samples) include MT3, SERPINA3, and glial fibrillary acidic protein (GFAP)." (PMID 38866016, 2024). "MT3 is related to chemotherapy resistance, which may be caused by its promotion of YAP1 expression and induction of tumor cell stemness." (PMID 38041044, 2023). "We performed differential gene expression analysis of samples from tumor patients with high and low expression of MT3, we subsequent analysis revealed that the differentially expressed genes were enriched in the response to oxidative stress and DNA damage-related pathways." (PMID 38041044, 2023). "And with the downregulation of MT3 often accompanying the methylation, there was speculation that MT3 may suppress the tumor via promoting hypermethylation." (PMID 35705729, 2022). "However, recently, in pediatric acute myeloid leukemia, MT3 was shown to function as a putative tumor suppressor gene by inhibiting proliferation and inducing apoptosis via the upregulation of forkhead box protein 1 (FOXO1)." (PMID 32843100, 2020). "The effect of MT3 on tumor growth in vivo was evaluated using xenografts in BALB/cAnN-Foxn1NU mice." (PMID 30813460, 2019). "However, MT3‐MMP positivity was largely seen in cells within the horny pearl in tumor tissues of moderately and well‐differentiated ESCC." (PMID 27292876, 2016). "Interestingly, other studies that have analyzed the immunoreactivity of MT3 in tumor sections have only reported its cytoplasmatic localization." (PMID 25933064, 2015). "Significant downregulation of MT3 has been most frequently reported in tumors that exhibiting MT3 methylation, suggesting that MT3 may act as a tumor suppresser via promoter hypermethylation." (PMID 24962166, 2014). "However, when overexpressed, both MT1- and MT3-MMP mediate cell invasion in cross-linked fibrin gel, a provisional form of extracellular matrix commonly deposited within tumor tissues and perivascular spaces in vivo." (PMID 22164270, 2011).
tumor (continued). "MT1- and MT2-MMP (MMP15) can each drive tumor cell invasion through basement membranes and the collagen type I-rich interstitial stroma, while MT3-MMP (MMP16) cannot efficiently cleave native collagen type I or confer cells with collagen-invasive ability in vitro or in vivo." (PMID 22164270, 2011). "Moreover, DNA methylation of MT3 from − 127 to − 8 sites was shown to be significantly correlated with advanced tumor stages and lymph node metastasis, implying that the methylation of promoter regions may be involved in tumor progression." (PMID 30139373, 2018). "By analyzing available RNA-Seq libraries containing paired tumor vs. adjacent healthy tissue data, we found that HCC cells express a considerably higher amount of MT3." (PMID 38594765, 2024). "We also observed that MT3 increased the expression of YAP1, potentially contributing to chemotherapy resistance by inducing tumor stemness through YAP1." (PMID 38041044, 2023). "Together, as a tumor suppressor in ESCC, MT3‐MMP down‐regulation represents an unfavorable factor for prognosis of patients with ESCC." (PMID 27292876, 2016). "Conversely, genes encoding proteins involved in cell growth arrest (i.e. DDIT3, MT3, SYK) are expressed in the invasive rim subpopulations of GBM specimens as compared to their matched tumor core." (PMID 23967279, 2013). "However, our spatial analysis of patient specimens shows increased MT3 expression and expression of the reactive gliosis marker GFAP at the tumor/stroma interface." (PMID 38866016, 2024). "In contrast, no or very low MT3‐MMP staining was detected in tumor tissues of poorly differentiated ESCC." (PMID 27292876, 2016). "Last, as the clinical findings indicated that down‐regulation of MT3‐MMP was significantly associated with ESCC metastasis, a wound healing assay was thus performed to assess the effect of MT3‐MMP on migration of human ESCC cells, reflecting metastatic potential of tumor cells in vitro." (PMID 27292876, 2016). "Moreover, down‐regulation of MT3‐MMP also enhanced colony‐forming and cell migration activity of ESCC cells, while overexpression of MT3‐MMP impaired these capabilities of tumor cells." (PMID 27292876, 2016). "In addition, although MT3‐MMP was expressed in moderately and well‐differentiated ESCC tissues, it was primarily localized within the horny pearl of tumor tissues." (PMID 27292876, 2016). "In some representative cases whose MT3‐MMP mRNA levels were markedly higher in nontumor than tumor tissues, Western blot analysis confirmed down‐regulation of MT3‐MMP at protein level in ESCC tumors." (PMID 27292876, 2016). "In this context, down‐regulation of MT3‐MMP was found in tumor tissues, when compared to their paired nontumor tissues, in 66.3% (57/86) of ESCC patients." (PMID 27292876, 2016). "An interesting finding in subsequent studies was that MT-3 mRNA and protein was not expressed in the Cd+2 and As+3 transformed cell lines, but was expressed in the tumor transplants generated by these cell lines in immunocompromised mice." (PMID 21303554, 2011). "There was not a significant difference in MT3 expression between the tumour and the margin from patients with unmethylated tumour." (PMID 16351731, 2005). "Methylation or down-regulation of MT3 did not correlate with and patient age, gender, smoking or drinking history, tumour stage, volume, lymph node involvement, or patient survival." (PMID 16351731, 2005). "MT3 gene expression was analysed by quantitative real-time RT-PCR in 29 of the primary tumours and their matched non-cancerous proximal resection margins for which RNA was available." (PMID 16351731, 2005). "Despite this, the importance of MT3 expression changes in tumour is not understood yet." (PMID 30932010, 2019). "Our study suggests that MT3 expression in the bladder cell lines could be dependent on the cell type but not relevant to the extent of neoplasia in vitro." (PMID 30813460, 2019).
tumor (continued). "No nuclear MT-3 expression pattern could be seen in the keratinocytes of normal skin epidermis, AK, or in the tumor cells of BCC and SCC." (PMID 25015776, 2015). "Urinary cytology for MT-3 positive cells would not improve the diagnosis of urothelial cancer, but might have potential as a biomarker for tumor progression." (PMID 21303554, 2011). "This study provides first evidence that in contrast to expression of MT3‐MMP in nontumor (normal) esophageal tissues, MT3‐MMP was down‐regulated at both mRNA and protein levels in primary ESCC tumor tissues, particularly those that were poorly differentiated." (PMID 27292876, 2016). "To date, minimal information is available about any functions of endogenous MT3-MMP in tumor cells, and the relevant ECM and non-ECM substrates for MT3-MMP remain poorly defined." (PMID 22164270, 2011). "We observed that MT3 expression was frequently down-regulated in primary oesophageal SCC when compared to normal mucosa, and significant down-regulation was most commonly observed in those tumours that were methylated for MT3, and not unmethylated tumours." (PMID 16351731, 2005).